NGF (nerve growth factor)
Diseases named in the same sentence as NGF in open-access papers (continued):
Sharing a sentence is not in itself a finding about the gene and the disease.
depression (continued). "There were no changes in its level after treatment with antidepressants, even though patients with severe depression had the lowest level of NGF." (PMID 35163141, 2022). "Before treatment, the serum levels of BDNF and NGF in patients with depression were 68.18 ± 16.37 (ng/mL) and 75.44 ± 18.59 (ng/mL), respectively." (PMID 35069013, 2022). "Animal studies show both BDNF and NGF to be active in various experimental models of depression, wherein BDNF is active even with a single administration, while a chronic administration is required for the manifestation of the NGF antidepressant-like effect." (PMID 35337082, 2022). "Lithium-induced pharmacological effects were explained by replenishment with BDNF and NGF in patients with depression." (PMID 35892326, 2022). "The data suggested that decreased expression levels of BDNF, GDNF, and NGF were concordant with the increased anxiety and depression-like behaviours in aged male mice offspring conceived by ART." (PMID 34605773, 2021). "VGF nerve growth factor concentrations have been found to be altered in depression, normalizing after antidepressant therapy, but only in clinical responders." (PMID 33255237, 2020). "Brain-derived neurotrophic factor (BDNF), vascular endothelial growth factor (VEGF), fibroblast growth factors (FGF) and VGF nerve growth factor are all involved in the pathophysiology of depression and are modulated by antidepressants." (PMID 33255237, 2020). "Reduced levels of circulatory NGF have previously been reported in patients with depressive disorders." (PMID 32842964, 2020). "Clinical studies showed reduced level of NGF in patients with major depressive disorder compared with healthy controls, and a study with suicide victims showed also decreased NGF in the hippocampus." (PMID 30767081, 2019). "On the other hand, the decreased NGF level of patients with major depressive disorder decreased further after duloxetine administration." (PMID 30767081, 2019). "Lower NT concentrations, such as serum BDNF and NGF have been shown to correlate negatively with many affective disorders including bipolar disorder, major depressive disorder, mania and obsessive compulsive disorder." (PMID 30767081, 2019). "Ethyleicosapentaenoate (EPA) has been used to treat depression, and such an activity likely originates from suppression of inflammation and upregulation of nerve growth factor (NGF)." (PMID 31312123, 2019). "On the other hand, the key regulator/signature for depression (e.g., nerve growth factor (NGF)) was labelled with biotin." (PMID 29681968, 2018). "It has been suggestedthat the reduced level of NGF in blood serum should be regarded as a biomarkerfor major depression." (PMID 28740732, 2017). "Nevertheless, the results were noteworthy because this novel study systematically investigated the correlations of depression after ischemic stroke with the following factors: neurotransmitters, inflammatory cytokines, NGF, CGRP, and lesion site in the brain." (PMID 29149884, 2017). "The data regarding NGF involvement in depression have been more sparse than those involving BDNF and FGF-2." (PMID 23675319, 2013). "In addition, preclinical and clinical models of depression have shown that antidepressants can control depression via NGF." (PMID 40869303, 2025). "NGF levels in blood samples are decreased in patients with major depressive disorder (MDD)." (PMID 40783715, 2025). "Inflammatory responses also play a role in depression, and NGF can alleviate inflammatory responses, which may have an effect on depression treatment." (PMID 40226675, 2024). "Dysregulation of NTFs, particularly brain-derived neurotrophic factor (BDNF), ciliary neurotrophic factor (CNTF), glial cell line-derived neurotrophic factor (GDNF), and nerve growth factor (NGF), has been implicated in various cerebral disorders, including epilepsy and depression." (PMID 39474368, 2024).
depression (continued). "In the current work, the mechanisms underlying the antidepressant effect of RGZ, such as regulation of AMPK and mTOR, and their downstream signaling pathways of pAKT, p38MAPK, 4EBP1, and NGF, were investigated in a mouse model of depression induced by dexamethasone (DEXA)." (PMID 36979839, 2023). "The reduced levels of nerve growth factor (NGF) are involved in the pathophysiology of depression." (PMID 36986674, 2023). "Interestingly, serum nerve growth factor levels have previously been observed to be significantly reduced in individuals with major depressive disorder, compared to control samples." (PMID 38004235, 2023). "Despite this, it is unknown if ACEs and ROI are associated with the stimulated production of NGF, SCF, SCGF, HGF, and M-CSF and if alterations in these growth factors mediate the effects of ACEs on the depression phenome." (PMID 37509019, 2023). "NGF is also a neurotrophin, and serum NGF levels are low in patients with depression." (PMID 37631092, 2023). "In addition, a randomized controlled clinical study of patients with depression found that HMs improved serotonin, brain-derived nerve growth factor, neuroendocrine factors, and depression symptoms." (PMID 37631092, 2023). "However, to our knowledge, there is no previous TMS study on it and even the evidence of the effect of antidepressant drugs on modulating depression via the NGF both preclinical and clinical models of depression are conflicting." (PMID 36979937, 2023). "This study tested the hypothesis that rosiglitazone (RGZ) has an antidepressant impact on dexamethasone (DEXA)-induced depression by analyzing the function of the pAKT/p38MAPK/mTOR pathway and NGF through regulation of AMPK." (PMID 36979839, 2023). "The findings suggest that a reduction in NGF during the acute phase of severe depression may result in heightened neuro-affective toxicity." (PMID 37509019, 2023). "Similarly, the decreased expression of NGF and BDNF in our study was confirmed by clinical and animal studies, in which it has been suggested that depression is associated with the neuronal atrophy caused by low levels of neurotrophins in the hippocampus." (PMID 36835228, 2023). "The first main conclusion of this study is that NGF levels are much lower in MDD, particularly in MDMD, and that the ratios of NFG to the immune-associated neurotoxicity index are significantly lower in both depression subtypes." (PMID 37509019, 2023). "Thus, a 14 day subcutaneous NGF injection in Flinders Sensitive rats (a genetic model of depression in animals) is known to promote a statistically significant active swimming time increase in the forced swim test." (PMID 35337082, 2022). "However, other studies have shown that, compared to healthy individuals, low levels of NGF were found in the hippocampus in patients with depression, which is contradictory to the high concentration of NGF in psoriasis." (PMID 35054853, 2022). "Declined NGF serum levels can be served as a possible biomarker of major depression disorder." (PMID 35069013, 2022). "Xiaoyao pills also has anti-inflammatory effect, which may relieve depression symptoms by inhibiting inflammatory reaction or activating NGF/BDNF-TRKA/TrkB-CREB pathway." (PMID 36569324, 2022). "It has been previously propounded that patients suffering from depression may have decreased levels of NGF and BDNF, and fluoxetine might increase those levels." (PMID 34991456, 2022). "Additionally, the study suggested that augmented MBCT following pharmacotherapy elevated the serum levels of BDNF and NGF in depression patients." (PMID 35069013, 2022). "The present study aimed to analyze the effects of augmented MBCT along with standard treatment dominated by pharmacotherapy on psychological state, compliance, brain-derived neurotrophic factor (BDNF), and nerve growth factor (NGF) expression levels in patients with depression." (PMID 35069013, 2022).
depression (continued). "Moreover, studies on animal models showed that an increase in BDNF and NGF expression is effective in improving memory impairment and depression." (PMID 33804892, 2021). "There is also decreased neurogenesis and neuroplasticity in people experiencing depression, the opposite of which can be inferred to occur in romantic love because of its substantial neurobiological activity and elevated nerve growth factor." (PMID 33912094, 2021). "Kaempferol promotes the protein expression of brain-derived neurotrophic factor (BDNF) and nerve growth factor (NGF) in hippocampal tissue from aged rats with chronic stress/depression, and these changes resulted in neuroprotection and improved depression-like behaviour." (PMID 34471414, 2021). "Based on published GWASs and candidate gene studies, the NGF gene might be a useful biological marker for the manic state and early detection of conversion from significant depression to BD." (PMID 33815158, 2021). "Contrary to our results in SDS, some studies have reported reduced NGF expression in depression." (PMID 34393735, 2021). "It is difficult to state unequivocally whether peripheral NGF may be only the result of stress response in depression, or whether it is an etiological factor of these mood disorders." (PMID 33804468, 2021). "It has numerous pharmacological effects including immunomodulatory, anti-tumour, anti-microbial, anti-aging and stimulation of nerve growth factor (NGF) synthesis, but little is known about its potential role in negating the detrimental effects of oxidative stress in depression." (PMID 33176761, 2020). "Thus, this study investigated the impact of regular leisure-time physical activity on cognitive function (plasma BDNF, NGF, and cathepsin B) and menopausal parameters (the climacterium, depression, and cognitive tests) in obese, middle-aged women." (PMID 33233633, 2020). "Interestingly, when controlling for pre-displacement exposures, higher levels of BDNF and NGF were associated with worse scores on validated scales for PTSD, depression, and anxiety." (PMID 32142533, 2020). "BDNF and NGF are among the best characterized neurotrophins in terms of its role in synaptic plasticity, as well as its potential role in the pathology and treatment of a variety of psychiatric disorders including depression." (PMID 30155683, 2019). "Finally, we investigated the mRNA expression of the neurotrophic factors nerve growth factor (NGF) and glial cell line-derived neurotrophic factor (GDNF) that have both been discussed to be implicated in chronic stress/depression as well as in nociception." (PMID 30142161, 2018). "Likewise, several studies have found the NGF levels to be significantly lower in the severe depression group than in the normal control group." (PMID 29149884, 2017). "Other studies showed that elevated serum NGF levels could significantly ameliorate the depression symptoms and improve the quality of life." (PMID 29149884, 2017). "This retrospective study was conducted on Chinese patients to systematically investigate the correlations of depression development 1 week after ischemic stroke with the following factors: intracerebral neurotransmitters, inflammatory cytokines, NGF, CGRP, and lesion site in the brain." (PMID 29149884, 2017). "On thebasis of the comorbidity of diabetes and cognitive impairment and depression,we modeled streptozotocin-induced diabetes in mice and studied the effect ofGK-2, the original NGF mimetic, on the cognitive impairment and depressive-likebehavior in these animals." (PMID 28740732, 2017). "To determine whether CGRP–mediated NGF was responsible for improvements in depression–like behavior, we examined the effects of K252a treatment." (PMID 26251188, 2015). "A large number of evidence show that chronic stress can lead to anxiety- and depression-like behaviors and may influence the distribution of NGF, both in animal models and in humans." (PMID 22474604, 2012).
depression (continued). "However, in another dexamethasone-induced depression model, rosiglitazone exerts antidepressant effects via NGF activation and decreases the levels of phosphorylated AKT and mechanistic target of rapamycin kinase (mTOR), which conflicts with the conclusions above." (PMID 40783715, 2025). "It is now considered that NGF may also be involved in the pathogenesis of depression." (PMID 40869303, 2025). "However, we next addressed whether activation of the BDNF/TrkB or NGF/TrkA signaling axis leads to the phosphorylation of Tau or Akt kinases in mice because of their critical role in depression like-behavior and memory decline." (PMID 39574138, 2024). "Consequently, NGF and its indices are integral components of the severity of recurrent depression." (PMID 37509019, 2023). "NGF plays an important role in the pathogenesis of depressive symptoms and the response to antidepressant treatment, which can be seen from that exogenous NGF could induce antidepressant-like effects in rodent depression models." (PMID 37089920, 2023). "Furthermore, subcutaneous NGF injections have been reported to alleviate depression." (PMID 36979839, 2023). "Therefore, in a group of mice already submitted to a behavioral test of depression, we examined the expression of some neurotrophic/growth factors associated with the pathogenesis of depressive disorders, such as BDNF, IGF-1, nerve growth factor (NGF), and fibroblast growth factor 2 (FGF-2)." (PMID 37298063, 2023). "Similarly, alteration in circulating NGF levels have been detected in patients with depression." (PMID 33066277, 2020). "The identification of higher NIHSS scores, higher HAMD scores, lower dopamine level, lower 5-hydroxytryptamine level, higher tumor necrosis factor-α level, and lower nerve growth factor level might be useful for clinicians in recognizing and treating depression in patients after a stroke." (PMID 29149884, 2017). "Furthermore, K252a blocked the antidepressant-like effects of CGRP, indicating that CGRP-induced NGF may rescue depression-like behavior." (PMID 26251188, 2015). "Thus the dysregulation of the neurotrophin systems, such as differential expression of genes involving in signaling by NGF (nerve growth factorA) and neurotrophin signaling pathway, may be involved in the pathophysiology of depression." (PMID 22348066, 2012). "For example, IL-1 induces depression by decreasing the mRNA and protein levels of BDNF and NGF, and decreasing the expression of the neurotrophin TrK receptor in the hippocampus, affecting the survival of neurons." (PMID 40530060, 2025). "Biomarkers known to play a role in depression, such as BDNF, NGF, VEGF, IGF1, Ang, Nrg1, IL-6, and TNF-α, will be measured using advanced techniques like enzyme-linked immunosorbent assay (ELISA), Western blotting, and immunoprecipitation kits." (PMID 41149800, 2025). "Since our previous studies showed an association of the functional SNP rs6265 in the BDNF gene with depression and response to therapy, we decided to extend the investigation and test additional SNPs in the BDNF gene, NGF, and NRG1." (PMID 40869303, 2025). "Abnormal oxidative stress and inflammation in patients with depression impair neuroplasticity by inhibiting the expression of BDNF and NGF." (PMID 39114351, 2024). "In the FS induced depression mouse model, acupuncture at GV20 and EX-HN3 significantly increased the expression of nerve growth factor (NGF), BDNF, NT-3, and NT-4/5." (PMID 39367470, 2024). "Therefore, it is plausible that BDNF and NGF, which were found to be upregulated here, could mediate the improved cognitive function and the reduced depression/anxiety-like behavior observed at long-term post-reperfusion by the combined Zn and Se administration or Zn administration alone." (PMID 38707461, 2024).
depression (continued). "It is thus not surprising that the focus of the pharmacological study on phytochemicals for the treatment of depression has been targeting neurotrophic factors, among which BDNF, GDNF, VEGF, and NGF are the most relevant neurotrophins." (PMID 37089920, 2023). "A number of the selected hub genes in our study have been previously reported to be related to FMS or depression, including GRIK1&2, NGF, KCNQ2, GRIA1, TRPV4, IL1A, and GABAA receptors." (PMID 37065490, 2023). "In the Flinders Sensitive Line (FSL) rat model of depression, electroconvulsive therapy (ECT) increased NGF levels in the hippocampus." (PMID 36979839, 2023). "Altered levels of other neurotrophins, such as neurotrophin–3 (NT–3), neurotrophin–4 (NT–4), and nerve growth factor (NGF), are also observed in patients with depressive disorders." (PMID 36978872, 2023). "Moreover, the lack of the NGF mimetics activity is most likely associated with a low density of TrkA receptors in the hippocampus and cortex, the main brain regions involved in the pathogenesis of depression." (PMID 35337082, 2022). "The present study aimed to analyze the effects of augmented MBCT combined with standard treatment (mainly pharmacotherapy) on depression patients about their psychological state, compliance, BDNF, and NGF expression levels." (PMID 35069013, 2022). "The decreased concentrations of BDNF, glial cell line-derived neurotrophic factor (GDNF), Artemin (ARTN), nerve growth factor (NGF), and vascular endothelial growth factor (VEGF) are a good repetitive finding in depression." (PMID 35369081, 2022). "This difference between NGF and BDNF mimetics is probably related to the differences in the TrkA and TrkB expression in the brain structures involved in the depression pathogenesis." (PMID 35337082, 2022). "A decrease in the nerve growth factor (NGF), as well as BDNF level, was found in the blood plasma of people suffering from depression and also in the hippocampus of suicide victims." (PMID 35337082, 2022). "Studies have shown that other neurotrophic factors, such as nerve growth factor (NGF) and BDNF, also play a key role in the neurophysiological mechanisms that relieve depression." (PMID 34040537, 2021). "Expression of NGF, BDNF, and REST genes at both protein and mRNA levels was lower in patients with depressive disorders than in the control group." (PMID 33804468, 2021). "Expression of the NGF, BDNF, and REST genes at both protein and mRNA levels is lower in patients with depressive disorders than in the control group." (PMID 33804468, 2021). "The levels of nerve growth factor (NGF) and glial cell line derived neurotrophic factor (GDNF) are decreased in depression and the magnitude of dysregulation of these factors correlates with depressive symptoms severity." (PMID 33255237, 2020). "By their nature NTs play a key role in preventing depressive disorders, and data obtained in rodent models of depression indicate that administration of BDNF and NGF have significant antidepressant effects." (PMID 33066277, 2020). "Using several depression-like animal models, we found that EDC exerted antidepressant effect via regulating neurotrophic factors such as NGF and BDNF." (PMID 33364963, 2020). "In the present study, by incorporating a depressed group of women as additional controls to the SSRI users we are able to show additive effects by depression and SSRI use on certain aspects of NGF signaling (ROCK2 and phosphorylated ROCK2)." (PMID 25611484, 2015). "Other parts of the signaling pathway, however, show opposing effects of depression per se and SSRI use, as in the case of NGF levels in endothelial cells." (PMID 25611484, 2015). "The current study merely focused on effects of antenatal depression and SSRI use during pregnancy on NGF signaling." (PMID 25611484, 2015).